MEF2C (myocyte enhancer factor 2C)
Diseases named in the same sentence as MEF2C in open-access papers (continued):
Sharing a sentence is not in itself a finding about the gene and the disease.
tumor (continued). "MEF2C-mediated VEGF-induced vasculogenic mimicry, angiogenesis, and invasion, as well as inhibition of β-catenin-induced tumor growth." (PMID 34733853, 2021). "In the presence of tumor-related factors, miR-223 can target MEF2C to inhibit tumor-induced MDSC differentiation from bone marrow cells, and then suppress tumor growth." (PMID 34084160, 2021). "MEF2B, MEF2C, and MEF2D are predominantly involved in tumor proliferation, migration, and invasion and in tumor immunity." (PMID 33863999, 2021). "Our analysis of the brain parenchyma revealed that MEF2C is highly expressed in BCBM and that its expression increases with tumor progression." (PMID 31930767, 2020). "It has been discovered that increased PGE2 in the tumor microenvironment leads to miR-223 down-regulation in MDSCs and subsequent up-regulation of its target myeloid enhancer factor 2 (Mef2c), which promote MDSC survival and accumulation in tumor site." (PMID 25538892, 2014). "VEGF selectively induces the production of the PRL-3-iso2 transcript mediated by the transcription factor MEF2C, suggesting an important role for both MEF2C and PRL-3 in endothelial cells function, and in particular in tumor angiogenesis." (PMID 22073279, 2011). "Notably, SOX18 appears to function as a central node within a transcriptional network involving MEF2C, p-STAT3, and VCAM1—particularly in the tumor vasculature and invasive front—underscoring its relevance to tumor microenvironment remodeling." (PMID 41373817, 2025). "It is known that a key step in metastatic development is the ability of tumor cells to invade the surrounding tissue and, to our knowledge, MEF2C has not been directly related to the migratory capability of TNBC cells." (PMID 37762600, 2023). "Collectively, these results point to the partial occurrence of EMT in TNBC cells, determined by MEF2C, while the overexpression of miR-194-5p resulted in a decline in TNBC cells’ aggressive behavior and reinforces this miRNA’s role as a tumor suppressor in TNBC." (PMID 37762600, 2023). "In the regulatory network, several hub genes with maximum intramodular connectivity were identified (i.e., GATA6, SOX17, MEF2C, and SRF), which might propose novel insights for tumor angiogenesis." (PMID 34869004, 2021). "The structure of the MEF2A gene is highly homologous to that of the MEF2C gene, and MEF2A plays a key role in embryonic development similar to MEF2C; however, MEF2A is poorly characterized and has been rarely studied in the context of tumor progression." (PMID 33863999, 2021). "Tumor markers IRF4, SOX17, and MEF2C are all involved in the development of various tumors." (PMID 32420368, 2020). "If energy release within the tumor cells occurs as a consequence of gradual activated processes, then MNDA should be transcribed first and MEF2C expression may be regulated by MNDA and its interactors." (PMID 22952604, 2012). "Consistent with this, tumors 98-031, 7105 and 86-277 also had insertions near the Mef2c-cooperating gene Sox4, although only the insertion in tumor 7105 was clonal (data not shown)." (PMID 19461887, 2009). "A possible explanation for these contradictory reports could be that TCF1 may act as a tumor suppressor in certain subgroups of pediatric T-ALL [including Early T-cell precursor (ETP)-ALL and myocyte enhancer factor 2C (MEF2C) positive T-ALL] and as an oncogene in other groups of T-ALL." (PMID 32046053, 2020). "The most significant, predicted activated upstream regulators in OS-2 (worse prognosis), relative to OS-1 tumor xenografts, were CEBPB and NFKB1 (P-value 5.54E–10 and 3.94E–09, respectively), whereas the most significant predicted inhibited upstream regulator was MEF2C (P-value 2.54E–23)." (PMID 27874835, 2016). "Interestingly, the inhibition of ActA activity led to preserving muscle mass, together with MEF2C muscle expression in KPC mice, without effects on tumor growth." (PMID 35406681, 2022).
cancer (52 papers, 2007 to 2025). A tumor composed of atypical neoplastic, often pleomorphic cells that invade other tissues. "Low expression of MEF2C has been confirmed to be associated with multiple muscle atrophy conditions, including cancer cachexia-induced skeletal muscle wasting." (PMID 36408215, 2022). "Since MEF2C nuclear translocation was reported to promote the transcription of its target genes vegf and mmp10, MEF2C seems to have an important role in cancer-associated signaling pathways." (PMID 33673112, 2021). "Once MEF2C is being produced, then activation of its many transcription targets should cause abnormal regulation in the already mentioned cancer and metabolic related pathways, thus causing diseased cellular states and, ultimately, carcinogenesis." (PMID 22952604, 2012). "In this study we demonstrate a novel association between dysregulated MEF2C gene expression and prominent ultrastructural changes in muscle structural integrity and mitochondria in cancer cachexia." (PMID 22361433, 2012). "Besides, MEF2C was upregulated in gefitinib-resistant cancer tissues and associated with gefitinib resistance in hepatic cancer cells." (PMID 34733853, 2021). "SLC39A14-mediated zinc acculation in muscle progenitor cells represses the expression of class I myosin and myocyte enhancer factor 2C and prevents muscle-cell differentiation and induces myosin heavy chain loss, which leads metastatic cancer promoting cachexia." (PMID 32744318, 2020). "Interestingly, many of the identified DMRs within the signature are localized close to genes already associated with cancer, such as MEF2C and TAF4." (PMID 25261372, 2014). "The genes MACC1, PEG10, CALCOCO1, and MEF2C have been found to be implicated in cancer." (PMID 24086395, 2013). "The activity of GATA‐family and MEF2C TF was upregulated in luminal cancer cells, while that of the ATF (BATF/MAFK/MAFF/BACH1) TF was upregulated in basal cancer cells." (PMID 38582099, 2024). "In fact, MEF2C’s dysregulation has been correlated with different diseases, including several types of cancer." (PMID 37762600, 2023). "Regarding cancer metastasis, a recent study reported that MEF2C was consistently expressed in breast cancer brain metastases, and that its nuclear translocation was related to brain metastatic disease severity via VEGFR-2 and β-catenin signaling." (PMID 36128051, 2022). "Although our work investigated the potential role of MEF2C in slow fiber atrophy during cancer cachexia, the atrophy of fast fibers and the role of factors other than ActA to explain it is more than likely." (PMID 35406681, 2022). "Although Mef2c is expressed at very low levels in Tregs, Mef2c-/- mice rapidly reject heart allografts and restrain cancer growth in syngeneic models, similarly to Mef2d-/- mice." (PMID 34290714, 2021). "Despite its recognized functions in several types of cancer development and progression, the role of MEF2C in BC, and particularly in BCBM, is still unexplored, raising interest in its study in BCBM." (PMID 33673112, 2021). "Myocyte enhancer factor 2C (MEF2C) is a transcription factor that is associated with the super-enhancer activity and cancer progression of Epstein–Barr virus infection." (PMID 32223537, 2020). "Fasn is associated with cancer metabolism and was downregulated dramatically in SAHA/JQ1-treated cells, whereas Cpt1a and Cpt1b and the muscle differentiation factor Mef2c were elevated." (PMID 30382078, 2018). "High levels of CXCR5 and MEF2C expression are typical for both cell lines, according to Broad-Novartis Cancer Cell Line Encyclopedia." (PMID 27909439, 2016). "Together, this evidence suggests a possible pro-cancer role of MEF2C in the development of OS." (PMID 40922352, 2025). "CNR1, DHCR24, DPP6, and MEF2C were strongly correlated with disturbances in executive functioning, episodic memory, and visuospatial functioning, which deregulate expression in multiple human cancers contributing to the antioxidant and repairing activity." (PMID 36518809, 2022).
cancer (continued). "In addition, MEF2C has close connections with uncontrolled cancer cell proliferation and enhanced invasion." (PMID 36128051, 2022). "In conclusion, we identified new microRNA–mRNA interactions, such as miR-27a/Foxo1, miR-27a/Mef2c, miR-27b/Cxcl12, miR-27b/Mef2c, miR-140/Cxcl12, miR-199a/Cav1, and miR-199a/Junb, that may contribute to muscle wasting in cancer cachexia." (PMID 31013615, 2019). "We further predicted new microRNA–mRNA interactions, such as miR-27a/Foxo1, miR-27a/Mef2c, miR-27b/Cxcl12, miR-27b/Mef2c, miR-140/Cxcl12, miR-199a/Cav1, and miR-199a/Junb, which may contribute to muscle wasting in cancer cachexia." (PMID 31013615, 2019). "Specifically, our results suggest that microRNA/mRNA interactions miR-27a/Foxo1, miR-27a/Mef2c, miR-27b/Cxcl12, miR-27b/Mef2c, miR-140/Cxcl12, miR-199a/Cav1, and miR-199a/Junb may contribute to muscle wasting in cancer cachexia." (PMID 31013615, 2019). "Some microRNAs also mediate a cross talk between cancer and stromal cells as in the case of TAM-derived miR-223, which down-regulates Mef2c expression in neoplastic cells, leading to an increase of cancer cell invasion, probably through the involvement of the miR-223 – Mef2c – β-catenin pathway." (PMID 25743773, 2015). "Moreover, Mb has been known as a MEF2 transcriptional target; further establishing the role of MEF2C during cancer cachexia in compromising not only structural integrity but also energy metabolism." (PMID 22361433, 2012). "Moreover, Mef2c has been shown to be downregulated in different wasting conditions including cancer cachexia." (PMID 22361433, 2012). "Future research into molecular mechanisms for muscle loss and intervention strategies to correct the effects of dysregulated MEF2C would greatly enhance our understanding of cancer cachexia progression and ultimately benefit cancer patient quality of life by improving muscle strength." (PMID 22361433, 2012). "Therefore, MEF2C appears to have a dual effect on cancer cells’ migration." (PMID 37762600, 2023). "Our current study disclosed that MEF2C and TRIM15 could promote invasion and metastasis through cancer-related signaling pathways: the MEF2C-activated MAPK signaling pathway and the TRIM15-activated glycosaminoglycan biosynthesis chondroitin sulfate signaling pathway." (PMID 36661663, 2022). "Interestingly, Myocyte Enhancer Factor 2C (MEF2C) has been documented in pathways of organelle biogenesis and maintenance and transcriptional misregulation in cancer, which involved DNA-binding transcription factor activity and protein heterodimerization activity." (PMID 36661663, 2022). "MEF2C is a member of the MEF2 protein family that was initially associated with the development of heart and muscle and is now known to have close connections with biological features that are characteristic of cancer, like uncontrolled proliferation and enhancement of invasion." (PMID 31930767, 2020). "Adding cancer patient serum to the muscle differentiation evaluation system significantly reduced the expression levels of TNNT, MyoD, MEF2C, and MYOG compared to the control." (PMID 40283883, 2025). "Although there is not any reports of MEF2C::SS18L1 in hematologic tumors at present, the presence of recurrent MEF2C::SS18 fusions in MSA suggests the importance and specificity of this fusion in pathogenesis of malignant tumor." (PMID 38907739, 2024). "The presence of dysregulated Nkx 2–5 is present in cancers such as ALL, because there it is working in a very different microenvironment and with different regulatory genes such as Mef2c-Nkx2–5 complex, which plays oncogenic role." (PMID 38110859, 2023). "Some genes consistently indicated a positive prognosis in different cancer types, such as CD20, ADAM28, MEF2C, CPNE5, and ATP2A3." (PMID 35634306, 2022). "Meanwhile, SLC25A13 and its neighboring genes were enriched in transcription factor target genes, including MEF2C, NCOA2, SNAI1, and SOX10 target genes, which were participated in the cancer progression." (PMID 35607442, 2022).
cancer (continued). "It is known that MEF2C is directly impacted by TGF-β signaling, and thus increasing the metastatic potential of cancer." (PMID 34367349, 2021). "Inhibitors abrogating FLI1, MEF2C, ELK3, or SP4 activation have been previously shown to have efficacy in different cancers." (PMID 33218352, 2020). "The absence of miR-524-5p in primary cancer tissue may promote bone metastasis through the upregulation of MEF2C." (PMID 36128051, 2022). "Therefore, we screened TF, proto-oncogenes, tumor suppressor genes, and other TAG from the genes adjacent to aberrant DNA methylation sites, of which multiple known cancer related genes, including MYC, DDR1, MEF2C, NDRG2, SIX1, TNFRSF10B and TSGA10, had HyperM phenomena." (PMID 26046465, 2015).
neurodevelopmental disorder (21 papers, 2016 to 2025). A behavioral and cognitive disorder with onset during the developmental period that involves impaired or aberrant development of intellectual, motor, or social functions. "Together, these studies provide key insight into the functions of MEF2C in human microglia in vitro and in vivo and suggest how loss of MEF2C contributes to key aspects of neurodevelopmental disorders and aging-related phenotypes." (PMID 41125877, 2025). "MEF2C deletion at 5q14.3 is the primary cause of MEF2C haploinsufficiency syndrome, which is typically associated with neurodevelopmental disorders." (PMID 39920775, 2025). "These serve as examples of the many gene regulatory networks implicated in neurodevelopmental disorders that are upstream or downstream of Mef2c." (PMID 39376213, 2024). "By screening de novo mutations in the 5′ UTR region of MEF2C in probands with neurodevelopmental disorder with hypotonia, stereotypic hand movements, and impaired language (NEDHSIL; OMIM: #613443), four variants creating upstream start codons were found." (PMID 36672937, 2023). "Dysregulation of this gene has been linked to neurodevelopmental disorders, including mental retardation, and the transcription activity of MEF2C is regulated by RhoA signaling in a kinase cascade that also involves ERK6." (PMID 34433918, 2021). "MEF2C haploinsufficiency caused by either large deletions encompassing MEF2C, or intragenic mutations of MEF2C, is associated with neurodevelopmental disorders." (PMID 30376817, 2018). "Together, these findings suggest that our iMG model of MEF2C loss may capture critical phenotypes of neuropsychiatric and neurodevelopmental disorders such as ASD." (PMID 41125877, 2025). "Conditional knockout of Mef2c in neuronal populations within the mouse brain causes many severe behavioral and synaptic phenotypes, while Mef2c haploinsufficiency caused by microdeletions in chromosome 5q14.3 have been linked to neurodevelopmental disorders." (PMID 37008050, 2023). "Furthermore, haploinsufficiency of the most downregulated gene in the subiculum, Mef2c, is associated with a neurodevelopmental disorder showing significant phenotypic overlap to patients with HNRNPU mutations." (PMID 37782669, 2023). "MEF2C (Myocyte-specific enhancer factor 2C) has been associated with neurodevelopmental disorders." (PMID 30376817, 2018). "In summary, we show here that Mef2c is required for proper synapse development on excitatory forebrain neurons, and its embryonic loss in these populations produces mice with behavior phenotypes reminiscent of multiple neurodevelopmental disorders, including ASDs and ID." (PMID 27779093, 2016). "This provides further support for the balance of excitatory and inhibitory synapses, which is affected by MEF2C disruption, representing a potential molecular mechanism for neurodevelopmental disorders." (PMID 39259737, 2024). "The MEF2C gene is responsible for neurodevelopmental disorders with hypotonia, stereotypic hand movements, and impaired language (MIM 613443)." (PMID 36393831, 2022). "We now investigated possible functional links between TCF4, MEF2C, ZEB2, UBE3A and ATRX which are all implicated in clinically overlapping, severe human neurodevelopmental disorders." (PMID 31988313, 2020). "It is well-described the MEF2C haploinsufficiency syndrome that has been recognized as a neurodevelopmental disorder." (PMID 31409060, 2019). "Here, we sought to evaluate the role of MEF2C in differentiated cortical excitatory neurons, and to determine whether loss of MEF2C function in these neuronal populations might produce behavioral and synaptic phenotypes with potential relevance to its associated neurodevelopmental disorders." (PMID 27779093, 2016). "In humans, MEF2C haploinsufficiency appears to be sufficient, at least in reported individuals, to produce this complex and severe neurodevelopmental disorder." (PMID 27779093, 2016).
neurodevelopmental disorder (continued). "Studies have reported that the lack of Mef2c, or mutations within these genes are associated with neurodevelopmental disorders." (PMID 32499679, 2020). "The differential regulation of local and callosal synaptic connections by postsynaptic MEF2C and FMRP, albeit in different directions, suggest that imbalances in local and long-range synaptic connectivity may contribute to different genetic causes of neurodevelopmental disorders." (PMID 34617509, 2021).